HSD17B7P2 (hydroxysteroid 17-beta dehydrogenase 7 pseudogene 2 )
Synonyms: HSD17B7; Hsd17b_2; bA291L22.1
Gene: Long non-coding RNA gene on chromosome 10 (38,356,356 to 38,378,505, forward strand). Ensembl gene ENSG00000290439.
Diseases named in the same sentence as HSD17B7P2 in open-access papers:
HSD17B7P2 is named in the same sentence as 6 diseases in open-access papers, as found by Europe PMC text mining. Sharing a sentence is not in itself a finding about the gene and the disease. The quoted sentences say what the papers report.
lung adenocarcinoma (1 paper, 2016). A carcinoma that arises from the lung and is characterized by the presence of malignant glandular epithelial cells. "Moreover, this work has identified several novel recurrent mutations in genes not typically associated with lung adenocarcinoma, which are each present in a significant subset of TCGA lung adenocarcinoma patients (e.g. IL32, LOC650368, HSD17B7P2 and RPSA)." (PMID 27933110, 2016).
adenocarcinoma (1 paper, 2014). A common cancer characterized by the presence of malignant glandular cells. "In 27 adenocarcinomas of never smokers, only three genes, EGFR, TBL3 and HSD17B7P2, occurred in two or more samples." (PMID 24894543, 2014).
HSD17B7P2 also shares sentences with these, for which no sentence is quoted: Alzheimer disease (1 paper); genetic diseases (1); legionellosis (1); pertussis (1).